TFAM (transcription factor A, mitochondrial)
Diseases named in the same sentence as TFAM in open-access papers (continued):
Sharing a sentence is not in itself a finding about the gene and the disease.
melanoma (continued). "To further explore that, we performed a global gene expression analysis between TFAM up and down groups from TCGA Metastatic Melanoma samples." (PMID 30242167, 2018). "The same authors also provided evidence that targeting TFAM may be a promising therapeutic approach to overcome resistance in melanoma." (PMID 33670365, 2021). "Additionally, we also found up-regulation of two metabolic biosynthesis key players, G6PD and ATP6AP1, in TFAM down samples, suggesting that TFAM levels influence the expression of genes coding for key components of metabolic pathways in melanoma." (PMID 30242167, 2018). "Furthermore, gene expression analysis in both melanoma cell lines and metastatic melanoma tumors suggested that the depletion of TFAM triggers angiogenesis via VEGF and is correlated with an invasion gene signature." (PMID 30242167, 2018). "As observed before, gene expression analysis showed that ASCT2, mainly responsible for glutamine uptake, was up-regulated in TFAM down melanoma lines, suggesting that these cells might rely more on glutamine metabolism than TFAM up melanoma lines." (PMID 30242167, 2018). "We then performed an upstream regulator analysis using Ingenuity Pathway Analysis software and collectively noted that the VEGF gene family is a predicted upstream regulator of the expression profiles of TFAM down melanomas (Activation Z-score = 3.838, p-value = 7.71E-10)." (PMID 30242167, 2018). "As a result, we found growth differences between TFAM up and down melanoma cell lines." (PMID 30242167, 2018). "Furthermore, by targeting TFAM, miR-181a/b replacement has a suppressive role in melanoma growth." (PMID 33670365, 2021). "Likewise, our proliferation analysis suggests that low TFAM melanoma cell lines may depend on glutamine availability to maintain optimum cellular growth." (PMID 30242167, 2018). "We also performed this experiment in other melanoma cell lines and observed similar results, supporting our hypothesis that TFAM down melanoma cell lines more readily require glutamine than lines with high TFAM expression." (PMID 30242167, 2018). "The privileged target of MiR-181a and -181b seems to be the mitochondrial transcription factor A (TFAM), known to be an oncogenic regulator of mitochondrial gene expression and metabolism in melanoma." (PMID 37174072, 2023). "Investigating negative-regulated target genes, we found eight genes (ANKRD13C, ARL5A, ATL3, PAWR, PDCD6IP, SLC16A7, TFAM, UBP1) presenting a significant inverse correlation with miR-181a/b expression also in melanoma A375 sensitive cells." (PMID 33670365, 2021). "In this case, the high OXPHOS phenotype was shown to rely on mitochondrial transcription factor A (TFAM), but not PGC1α, indicating that some melanoma cells adopt an elevated mitochondrial phenotype independent of the MITF-PGC1α signalling axis." (PMID 34830962, 2021). "To investigate the palbociclib-driven changes in mitochondrial metabolism, we examined mRNA expression or protein levels of key regulators of mitochondrial biogenesis in melanoma (MITF, PGC1α and TFAM) as well as protein levels of key components of the five mitochondrial OXPHOS complexes." (PMID 33572972, 2021). "The analysis showed a negative correlation of TFAM expression with invasive signature and a positive correlation with mitochondrial biogenesis in melanoma cell lines." (PMID 30242167, 2018). "In A375 human melanoma cells (which do not appear to express p16 constitutively), forced expression of p16 resulted in marked downregulation of ND4, SDHA and UQCRC2, while the reduction in PRC and TFAM was less striking." (PMID 28915557, 2017).
hepatocellular carcinoma (12 papers, 2013 to 2026). A malignant tumor that arises from hepatocytes. "Meanwhile, studies of human normal and malignant liver tissues and cell lines demonstrate that TFAM expression trends upward in Hepatocellular Carcinoma cells resistant to drugs." (PMID 38476236, 2024). "SIRT1 has been shown to promote OXPHOS and mitochondrial biogenesis in adipocytes and hepatocellular carcinoma cells by regulating the expression of mitochondrial transcription factor A (TFAM)." (PMID 35641987, 2022). "It has been reported that the oxidants such as tertiary butyl hydroperoxide (t-BOOH), an ROS mimic, increase cellular NRF1 and TFAM gene expression in rat liver cells and hepatoma cells." (PMID 31011285, 2019). "Previous studies have shown nuclear localization of TFAM in rat hepatoma cells, as well as an alternate isoform of TFAM in mouse testis nuclei." (PMID 23991223, 2013). "Additionally, TFAM was significantly downregulated in metastatic hepatocellular carcinoma (HCC) tissues and was associated with overall survival and tumor recurrence in HCC patients." (PMID 41362737, 2026). "Conversely, TFAM downregulation in gastric and hepatocellular carcinomas reduced proliferation." (PMID 41226485, 2025). "Moreover, it has been reported that ionizing radiation activates the DNA damage response (DDR) via ATM/p38, which causes HuR shuttling to the cytoplasm in order to stabilize mitochondrial transcription factor A (TFAM) mRNA and induce its expression in HepG2 hepatoma cells." (PMID 35681645, 2022). "In this study, ZNF281 knockdown increased the expression of mitochondrial transcription factor A (TFAM) in hepatocellular carcinoma (HCC) cells, accompanied with increment of mitochondrial content, oxygen consumption rate (OCR) and levels of TCA cycle intermetabolites." (PMID 37880213, 2023).
myocardial infarction (12 papers, 2012 to 2024). Gross necrosis of the myocardium, as a result of interruption of the blood supply to the area, as in coronary thrombosis. "Haplogroup TFAM gene variation, associated with low TFAM, was linked to early-onset myocardial infarction." (PMID 28122051, 2017). "TFAM also protects the heart from mtDNA deficiencies and attenuates left ventricular remodeling and failure after myocardial infarction created by ligating the left coronary artery." (PMID 26074984, 2015). "Overexpression of human TFAM in mice increases the amount of mitochondrial DNA and dramatically ameliorates the cardiac dysfunctions caused by myocardial infarction." (PMID 22469910, 2012). "Mitochondrial respiratory chain complex enzyme activity decreases in mice with myocardial infarction, and this phenomenon was revered in TFAM transgenic mice." (PMID 36172183, 2022). "In mice, human TFAM overexpression enhances the amount of mtDNA and prevents the cardiac dysfunctions induced by myocardial infarction." (PMID 33023026, 2020). "Overexpression of TFAM attenuates the decrease in mtDNA copy number after myocardial infarction, ameliorates pathological hypertrophy, and markedly improves the chances of survival." (PMID 26074984, 2015). "A positive effect on survival was observed after myocardial infarction leading to pathological hypertrophy in the case of transgenic mice with TFAM overexpression and even in the cardiac myocytes of a transgenic mouse model with overexpressed recombinant human TFAM." (PMID 32824374, 2020). "In addition, an improvement in survival in experimental conditions where human TFAM is overexpressed in an animal model of myocardial infarction." (PMID 31018497, 2019). "For instance, overexpression of the mitochondrial transcription factor A (TFAM) increases the amount of mitochondrial DNA, leading to myocardial infarction and resulting in reduced cardiac function." (PMID 39408732, 2024).
type 2 diabetes (12 papers, 2011 to 2026). "An increase in plasma IL-6 levels is associated with decreased TFAM protein production in liver biopsies in obese patients with and without type 2 diabetes." (PMID 33579000, 2021). "These genes can also be found to be methylated, with PGC1a modifications affecting mitochondrial density in type 2 diabetic patients, and NRF1 methylation causing TFAM (mitochondrial transcription factor A) silencing and a reduction in mitochondrial biogenesis." (PMID 33228792, 2020). "Our results demonstrated for the first time that Pg, a classical thiazolidinedione drug for type 2 diabetes treatments, can be used to efficiently promote mitochondrial biogenesis of hMSC by activating the PGC-1α/NRF1/TFAM pathway." (PMID 37723135, 2023). "Maternal diabetes, either pregestational type 2 diabetes or GDM, impair placental mitochondrial biogenesis (formation of new mitochondria), with decreased mitochondrial transcription factor A (TFAM) and peroxisome proliferator-activated receptor gamma coactivator 1-alpha (PGC1-α) expression levels." (PMID 37960276, 2023).
bladder cancer (8 papers, 2013 to 2024). "The present study aimed to elucidate the roles of TFAM and miR-590-3p and their association in bladder cancer cells." (PMID 24137381, 2013). "In vitro studies have shown TFAM to induce bladder cancer cell proliferation, migration, and colony formation." (PMID 36289714, 2022). "TFAM expression was significantly enhanced in bladder cancer cells and directly related to cancer stage." (PMID 36289714, 2022). "As the expression level of miR-590-3p was lower in the bladder cancer tissues and the expression of TFAM was higher, the effect of the transfection of miR-590-3p and TFAM on 5637 cell proliferation was studied using MTT assays." (PMID 24137381, 2013). "The present study reported that the expression of TFAM was significantly increased in bladder cancer, while the expression of miRNA-590-3p was downregulated." (PMID 24137381, 2013). "In summary, the present study identified miR-590-3p and TFAM transfection expression patterns in bladder cancer." (PMID 24137381, 2013). "The expression of TFAM in the bladder cancer tissues was significantly higher compared with the normal and adjacent tissues (P<0.05)." (PMID 24137381, 2013). "In bladder cancer, the mitochondrial transcription factor a (TFAM), is commonly overexpressed, and this overexpression frequently coincides with the down regulation of miR-590-3p which was identified to directly target TFAM." (PMID 24670365, 2014). "Furthermore, the present study investigated the molecular function of miR-590-3p and TFAM in the bladder cancer 5637 cell line." (PMID 24137381, 2013). "In conclusion, the present study suggested that TFAM, a direct target of miRNA-590-3p, may play a significant role in the tumorigenesis of bladder cancer and thus may be a promising target for cancer therapeutics." (PMID 24137381, 2013). "The loss of miRNA-159-3p, the endogenous TFAM inhibitor, may promote the aberrant expression of TFAM, contributing to the pathogenesis and progression of bladder cancer." (PMID 24137381, 2013). "Indeed, the present data showed that in bladder cancer, the expression of TFAM was significantly higher compared with the normal and adjacent tissues, indicating that TFAM may be associated with the growth of bladder cancer." (PMID 24137381, 2013).
cardiac hypertrophy (8 papers, 2019 to 2026). "A recent cell culture study demonstrated that miR-4458 negatively modulated cardiac hypertrophy, a known intermediate phenotype, and an independent risk factor for ischemic stroke, by activating mitochondrial transcription factor A (TFAM), a well-recognized myocardial protective protein." (PMID 38317187, 2024). "For example, rare variants −91 C→A in 5′-UTR exon 1 and the Ala105Thr missense mutation of TFAM were shown to be involved in the pathogenesis of cardiac hypertrophy and variants rs10826175 (A→G) SNP upstream and rs1937 (G→C) SNP in exon 1 of TFAM were associated with diffuse-type gastric cancer." (PMID 32824374, 2020). "In addition, EVO preserves mitochondrial function by increasing the activity of the PGC1α/NRF1/TFAM signaling pathway and inhibits the development of cardiac hypertrophy and fibrosis by attenuating TGFβ/IGFBP7/Col1a1 expression." (PMID 37009790, 2023). "Indeed, miR-4458 facilitated TFAM expression in cardiomyocytes to inhibit cardiac hypertrophy." (PMID 38317187, 2024).
cardiomyopathy (8 papers, 2012 to 2025). A disease of the heart muscle or myocardium proper. "Similarly, a beneficial impact was also evident in the m.C5024T tRNAAla mouse model, where moderate overexpression of TFAM and the associated mtDNA increase improved the cardiomyopathy phenotype in aged mice." (PMID 40587199, 2025). "In this mouse strain, knockout of Tfam in heart, which typically results in severe cardiomyopathy, was rescued by expression of the human TFAM gene." (PMID 29572490, 2018). "Likewise, increasing the absolute number of wild-type mtDNA copies via moderately increasing TFAM expression in the m.C5024T tRNAAla mouse model showed a beneficial effect on the cardiomyopathy phenotype in aged mice." (PMID 40587199, 2025). "Human TFAM expressed in mouse hearts with genetic deletion of their endogenous cardiac TFAM mature normally, are healthy and do not express a cardiomyopathy phenotype." (PMID 23075607, 2012).
depression (8 papers, 2020 to 2025). "IGF-1 can activate the CREB/PGC-1α signaling pathway to regulate the expression of genes such as NRF1, TFAM, and the mitochondrial dynamics-related protein Drp1, promoting mitochondrial biogenesis and improving function, ultimately alleviating depression." (PMID 40699781, 2025). "Taken together, these results suggest that hippocampal SIRT1 mediates the ameliorative effect of exercise on anxiety- and depression-like behaviors in APP/PS1 mice through the PGC-1α/NRF1/TFAM/mitochondrial biogenesis pathway." (PMID 39744519, 2024). "In total, hippocampal SIRT1 regulates the SIRT1/PGC-1α/NRF1/TFAM/mitochondria biogenesis axis to mediate the ameliorative effect of treadmill exercise on anxiety- and depression-like behaviors in APP/PS1 mice." (PMID 39744519, 2024). "Activated PGC-1α cooperates with NRF1/2 to upregulate TFAM expression, promoting the replication of mitochondrial DNA (mtDNA) and protein synthesis through the PGC-1α-NRF1/2-TFAM pathway, ultimately facilitating mitochondrial biogenesis and alleviating depression." (PMID 40699781, 2025). "Therefore, the SIRT1-dependent PGC-1α/NRF1/TFAM signaling pathway, which mediates mitochondrial biogenesis, plays a significant role in the intervention of anxiety and depression-like behaviors." (PMID 39744519, 2024). "Additionally, electroacupuncture therapy has been found to successfully improve depression-like behaviour and cognitive dysfunction while inducing the Nrf1/TFAM pathway after I/R injury." (PMID 39198723, 2024). "Although HEBP2 and SLC25A37 have been described to be involved in different diseases such as cancer, anemia, porphyria, or depression, we focused on TFAM for further studies due to its widely observed implication in different neurodegenerative disorders, PD being among them." (PMID 36674978, 2023). "Additionally, a study in an animal model of depression induced by prenatal stress found that the reduced level of PGC-1α protein in the hippocampus inhibits mitochondrial biogenesis through the PGC-1α/NRF1/TFAM pathway, leading to depressive-like behavior." (PMID 40699781, 2025). "Clinical evidence has found that the expression of PGC-1α and downstream genes TFAM and NRF1 is downregulated in the blood monocytes of patients with Major Depressive Disorder (MDD)." (PMID 40699781, 2025). "Finally, we investigated the effects of pharmacological activation of SIRT1 on anxiety- and depression-like behaviors, the SIRT1/PGC-1α/NRF1/TFAM signaling axis, and mitochondrial biogenesis." (PMID 39744519, 2024).
Hyperglycemia (8 papers, 2019 to 2025). An increased concentration of glucose in the blood. "Fibroblast haptotaxis declined under hyperglycemia or when GDF15 or TFAM were silenced, and skin reconstruction was blocked by GDF15 knockdown." (PMID 40174478, 2025). "Previous studies have shown that metformin upregulates TFAM expression in C2C12 myoblasts under hyperglycemia and in the placenta of mice with a high-fat diet." (PMID 36613786, 2022). "Studies have shown that chronic hyperglycaemia reduces the expression levels of PGC-1α and TFAM, while activation of PGC1-α and increased expression of TFAM protect against HG-mediated podocyte injury by promoting mitochondrial biogenesis." (PMID 36967383, 2023).
non-small cell lung carcinoma (8 papers, 2016 to 2026). A group of at least three distinct histological types of lung cancer, including non-small cell squamous cell carcinoma, adenocarcinoma, and large cell carcinoma. "In non-small cell lung cancer and gastric cancer cells, the depletion of TFAM resulted in cell cycle arrest, morphology changes and reduced proliferation." (PMID 39580766, 2024). "Interestingly, a study with non-small cell lung carcinoma suggested an anti-tumorigenic role of TFAM, whereas silencing of this gene triggered cell cycle arrest, inhibiting cancer cell proliferation and migration." (PMID 30242167, 2018). "Furthermore, TFAM expression has been associated with a negative outcome for patients with pancreatic and non-small cell lung cancer through the inhibition of apoptosis." (PMID 39580766, 2024). "The role of TFAM in non-small cell lung cancer (NSCLC) remains largely unknown." (PMID 26820294, 2016). "This hypothesis might be supported by the fact that the downregulation of TFAM expression has promoted ROS-dependent activation of JNK/p38 MAPK and apoptosis, as reported in non-small cell lung cancer." (PMID 29747444, 2018).
Cerebral ischemia (7 papers, 2015 to 2026). Restriction of arterial blood supply to the brain associated with insufficient oxygenation to support the metabolic requirements of the tissue. "Molecularly, the main regulator of mitochondrial biogenesis PGC-1α improved mitochondrial function by activating its downstream genes NRF1 and TFAM, thereby remitting cerebral ischemia–reperfusion injury." (PMID 38773376, 2024). "Previous research has suggested that TFAM may increase the biogenesis of mitochondria after cerebral ischemia and hypoxia." (PMID 38333750, 2024). "Compared with the global cerebral ischemia group, the sevoflurane post-conditioning group had much higher gene and protein expression levels of PGC-1α, NRF-1, and TFAM in the hippocampus after reperfusion." (PMID 27965539, 2016).
liver cancer (7 papers, 2021 to 2025). An epithelial or non-epithelial malignant neoplasm that arises from the liver. "Firstly, by analyzing the TCGA database, the results indicated that the expression of TFAM was directly associated with the advancement of liver cancer." (PMID 39770569, 2024). "The mRNA or protein expression of PSAT1 was positively associated with TFAM in CCLE liver cancer cell lines and liver cancer patient tissues." (PMID 36788227, 2023). "As previous studies found that TFAM and mtDNA levels differentially correlated with colorectal and liver cancer prevalence, the association between TFAM expression and HNC oncogenicity needs further determination." (PMID 34663785, 2021). "Additionally, HuR was found to reduce the sensitivity of liver cancer cells to radiotherapy by upregulaing the mRNA expression of mitochondrial transcription factor A (TFAM), which is linked to decreased radiosensitivity." (PMID 33513829, 2021). "TFAM is also upregulated in drug-resistant liver cancer cells, and inhibiting TFAM expression enhances the sensitivity of resistant cells to chemotherapy." (PMID 38589371, 2024). "Subsequently, analysis of liver cancer sample data from the TCGA database revealed a significant upregulation of TFAM in patients." (PMID 39770569, 2024). "In summary, these data indicated that OA had potential anticancer activity by targeting TFAM and eliminating drug-resistant cells in hypoxic microenvironments in liver cancer." (PMID 39770569, 2024). "Moreover, PSAT1 and TFAM were enriched in the invasive front of liver cancer tissues." (PMID 36788227, 2023). "Overall survival analysis further indicated that there was a negative correlation between TFAM and survival rate in liver cancer patients." (PMID 39770569, 2024).